USP4 (ubiquitin specific peptidase 4)
Diseases named in the same sentence as USP4 in open-access papers (continued):
Sharing a sentence is not in itself a finding about the gene and the disease.
lung carcinoma (23 papers, 2016 to 2025). "Studies have demonstrated that USP4 is closely associated with various malignant tumours, such as colorectal, breast, liver and lung cancers." (PMID 36969062, 2023). "Collectively, we concluded that the oncogenic property of USP15 and USP4 is associated with SRSF1 that shows a parallel regulatory effect in lung cancer cell while the alternatively spliced isoform SRSF1-3 lacks such oncogenic functions." (PMID 35027535, 2022). "The reduced expression of USP4 in lung adenocarcinoma and lung squamous cell cancer compared with normal samples is associated with poor survival among lung cancer patients." (PMID 33681193, 2021). "The low expression subgroup demonstrated shorter overall survival compared to the high expression subgroup, indicating that low USP4 expression is associated with poor lung cancer prognosis." (PMID 31936290, 2020). "To investigate the causative role of Twist1 in USP4-mediated lung cancer stemness, we performed the rescuing experiments." (PMID 32549341, 2020). "The relationship between Snail1 and USP4 expression in lung cancer was further investigated through OncoLnc analysis, which revealed an association between high Snail1 and low USP4 expression." (PMID 31936290, 2020). "Together, these findings indicate that USP4 is critically important in promoting lung cancer stemness and is associated with lung cancer clinical prognosis." (PMID 32549341, 2020). "Low expression of USP4 was associated with poor survival among lung cancer patients and was inversely correlated with expression of stemness and inflammation markers." (PMID 31936290, 2020). "The high Snail1 expression subgroup had shorter survival compared to the low expression subgroup in the first 3000 days, indicating that low USP4 expression is associated with poor lung cancer prognosis." (PMID 31936290, 2020). "In tissue samples from lung cancer patients, decreased expression of USP4 was associated with advanced cancer stage." (PMID 31936290, 2020). "When it comes to the reason causing downregulation of USP4 in lung cancer, snail 1 may take the major responsibility and lead to macrophage-dependent inflammation and therapeutic resistance." (PMID 32669974, 2020). "High expression of USP4/Twist1 is associated with poor clinical outcomes of lung cancer patients." (PMID 32549341, 2020). "Furthermore, higher levels of USP4 mRNA were significantly associated (p = 0.0294) with poor overall three-year survival of lung cancer patients." (PMID 32549341, 2020). "Importantly, our results showed clear clinical relevance, supported by the observations that expression of USP4 and Twist1 is positively correlated in lung cancers and that high expression of USP4/Twist1 is associated with poor overall survival in lung adenocarcinoma patients." (PMID 32549341, 2020). "High expression of USP15, along with its close paralog USP4, has been reported to promote lung cancer cell proliferation." (PMID 40762380, 2025). "TAM-secreted inflammatory cytokines (e.g., IL-1β and TNF-α) induce Snail expression in lung cancer cells, epigenetically downregulating USP4 to promote drug resistance, stemness and PD-L1 expression." (PMID 38715050, 2024). "To date, USP4 has demonstrated its potential as a prognostic biomarker across a spectrum of malignancies, including pancreatic cancer, multiple myeloma, and lung cancer." (PMID 39393052, 2024). "In lung cancer, USP4 was identified as a negative regulator of TNFα-mediated lung cancer cell migration through deubiquitination of TRAF2 and TRAF6." (PMID 38802791, 2024). "Reportedly, USP4 can be used as a prognostic biomarker because it is upregulated in diverse malignancies, including lung cancer, multiple myeloma, and pancreatic cancer." (PMID 37949874, 2023). "In summary, we found that the deubiquitinating enzymes USP15 and its close paralog USP4 regulate alternative splicing of SRSF1 resulting in the isoform-specific functions in lung cancer cell." (PMID 35027535, 2022).
lung carcinoma (continued). "In this study, we found that USP15 and USP4 regulate alternative splicing of SRSF1 resulting in the isoform-specific functions in lung cancer cell proliferation and migration." (PMID 35027535, 2022). "Here, we found that USP15 and its close paralog USP4 are overexpressed and facilitate lung cancer cell proliferation by regulating the alternative splicing of SRSF1." (PMID 35027535, 2022). "Collectively, our current study demonstrates USP15 and USP4 mediated lung cancer cell proliferation and migration by increasing the expression of functional full-length SRSF1 protein." (PMID 35027535, 2022). "In contrast, USP4 expression was suppressed by the EMT marker SNAIL 1 in the later stages of lung cancer that affected migration." (PMID 35884607, 2022). "Collectively these data suggest that both USP15 and USP4 genes are overexpressed and facilitate lung cancer cell progression." (PMID 35027535, 2022). "The connection between USP4 and NF-κB is identified in lung cancers where stable knockdown of USP4 augments inflammatory responses, stemness properties, chemoresistance, the expression of programmed death ligand 1, and tumor growth." (PMID 33681193, 2021). "Recently, USP4 was found to mediate deubiquitination of the epithelial–mesenchymal transition (EMT) transcriptional factor Twist1 to promote lung cancer cell stemness." (PMID 33681193, 2021). "For example, when lung cancer cells interact with macrophages, Snail1 is induced and subsequently silences USP4 by promoter methylation, contributing to the inflammation and stemness associated with macrophage-promoted tumor progression." (PMID 33681193, 2021). "Herein, we show that USP4 is critically important in promoting lung cancer stemness via stabilizing Twist1 expression." (PMID 32549341, 2020). "Snail1 was induced in lung cancer cells by interaction with macrophages, and epigenetically suppressed USP4 expression by promoter methylation." (PMID 31936290, 2020). "The effect of USP4 downregulation on the transforming capacity of lung cancer cells was further investigated using cell proliferation and anchorage-independent growth assays." (PMID 31936290, 2020). "Through analyzing TCGA database, USP4 mRNA level was significantly downregulated in lung cancer tissues." (PMID 32669974, 2020). "Further, mice injected with USP4 knockdown lung cancer cells demonstrated enhanced tumorigenesis and tumor growth." (PMID 31936290, 2020). "Stable knockdown of USP4 in lung cancer cells enhanced inflammatory responses, stemness properties, chemotherapy resistance, and the expression of molecules allowing escape from immunosurveillance." (PMID 31936290, 2020). "In this study, we demonstrate that USP4 is critically important in maintaining lung cancer cell stemness." (PMID 32549341, 2020). "Our data indicate that USP4 stabilizes Twist1 to promote lung cancer cell stemness, which prompted us to verify the clinical relevance of USP4–Twist1 in human lung cancer." (PMID 32549341, 2020). "Conversely, ectopic expression of USP4 significantly enhances lung cancer cell stemness, which is effectively rescued by simultaneous silencing of Twist1." (PMID 32549341, 2020). "Our results demonstrate that deubiquitinase USP4 promotes lung cancer cell stemness via upregulation of Twist1, Oct4 and Sox2 expression." (PMID 32549341, 2020). "In this study, we uncover that USP4 is a novel deubquitinase of Twist1 and that silencing of Twist dramatically inhibits USP4-induced stemness of lung cancer cells, suggesting that the USP4–Twist1 axis plays a critical role in lung cancer stemness." (PMID 32549341, 2020). "Together, our findings demonstrate that USP4 deubiquitinates and stabilizes Twist1 protein to promote lung cancer stemness." (PMID 32549341, 2020). "The low expression of USP4 in lung cancer cells and tumors results from Snail1-mediated epigenetic suppression." (PMID 31936290, 2020).
lung carcinoma (continued). "Silencing of USP4 significantly reduced Oct4 and Sox2 protein expression, suggesting that silencing of USP4 can inhibit lung cancer cell stemness." (PMID 32549341, 2020). "Together, this study highlights an important role for USP4 in lung cancer stemness and suggests USP4 as a potential target for lung cancer diagnosis and treatment." (PMID 32549341, 2020). "Consistent with OncoLnc results, the expression level of USP4 was significantly reduced in stage II to stage IV lung cancer tissues compared to normal human lung tissue." (PMID 31936290, 2020). "Together, these results demonstrate that Twist1 is a critical downstream effector in USP4-induced lung cancer stemness." (PMID 32549341, 2020). "In turn, downregulation of USP4 in lung cancer cells further promotes inflammation, stemness, and therapeutic resistance of cancer cells." (PMID 31936290, 2020). "There was also a significant difference in Snail1 expression between USP4 low (bottom 50%) and USP4 high (top 50%) lung cancer subgroups." (PMID 31936290, 2020). "According to database analysis, expression of USP4 was inversely correlated with expression of stemness markers in lung cancers." (PMID 31936290, 2020). "In this study, we demonstrate that the deubiquitinase USP4 is critically important in promoting lung cancer stemness." (PMID 32549341, 2020). "Together, these data indicate that USP4 is a critical factor to promote lung cancer stemness, which is dependent on its deubiquitinating enzymatic activity." (PMID 32549341, 2020). "Clinical analysis by Kaplan–Meier dataset showed that lung cancer patients with high USP4 or Twist1 levels exhibited poor overall survival (OS)." (PMID 32549341, 2020). "Together, these results indicate that the USP4–Twist1 axis plays a critical role in lung cancer stemness and clinical prognoses." (PMID 32549341, 2020). "USP4 is more abundant in metastatic lung cancer cells than in primary lung cancer cells, resulting in the increase in β-catenin expression through the inhibition of ubiquitin-mediated degradation." (PMID 31262974, 2019). "β-Catenin protein stability was significantly lower in USP4-silenced PC14PE6/LvBr4 cells than in PC14PE6 cells, demonstrating that USP4 positively regulated β-catenin expression in metastatic lung cancer cells." (PMID 26883469, 2016). "USP4 can serve as a double-edged sword in tumor progression because it functions as a tumor suppressor in lung cancer by indirectly circumventing stemness, while USP4 promotes TNBC metastasis by enhancing TGF-β signaling and inducing the suppressive activity of Tregs." (PMID 38715050, 2024). "In lung cancer tissues, USP4 can stabilize Twist1 to promote tumor cell stemness." (PMID 37251574, 2023). "We observed an increased expression of BIN1 through SRSF1 downregulation by USP15 and USP4 knockdown, which may, in turn, inhibits the metastatic ability of lung cancer cells." (PMID 35027535, 2022). "Furthermore, USP4 stabilizes Twist1 and results in enhanced tumorsphere formation and lung cancer stemness." (PMID 35884607, 2022). "USP4 has been reported to play a tumor-suppressing role in lung cancer up to date." (PMID 32669974, 2020). "Expression of USP4 were reduced at more advanced stages of lung cancer." (PMID 31936290, 2020). "In addition, overexpression of Snail1 promoted methylation of the USP4 promoter, suppressed promoter activity, and reduced USP4 expression in cultured lung cancer cells." (PMID 31936290, 2020). "Further analysis of data from the GEO database also revealed that USP4 expression was downregulated in different head and neck, breast, and lung cancer cells following enhancement of stemness by sphere formation, Bmi1 and Snail overexpression, or chemotherapeutic treatments." (PMID 31936290, 2020).
lung carcinoma (continued). "USP4 expression levels in various normal and cancerous tissue types were further investigated by analysis of data from Oncomine, which revealed lower USP4 expression in multiple head and neck, breast, and lung cancers compared to matched normal tissues." (PMID 31936290, 2020). "We then investigated the molecular bases by which USP4 promotes lung cancer stemness." (PMID 32549341, 2020). "In addition, USP4 expression is elevated in human lung cancer specimens and is positively correlated with Twist1 expression." (PMID 32549341, 2020). "Furthermore, we show that USP4 expression is elevated in human lung cancer specimens and is positively correlated with Twist1 expression." (PMID 32549341, 2020). "Database searches revealed higher expression of USP4 in therapy-resistant lung tumors; therefore, we further investigated whether downregulation of USP4 in lung cancer cells confers chemotherapy and immunotherapy resistance." (PMID 31936290, 2020). "The mechanisms of USP4 in lung cancer progression are complicated." (PMID 32669974, 2020). "In addition to the increased inflammation and stemness, knockdown of USP4 in lung cancer cells also increased resistence to chemotherapy drugs and expressing with higher level of PD-L1." (PMID 31936290, 2020). "Downregulation of USP4 increased the proliferation rates of all cell lines examined after 48 h as well as the number of colonies produced by these lines in soft agar after 3 weeks, indicating that USP4 downregulation enhances both the proliferative and transformation capacities of lung cancer cells." (PMID 31936290, 2020). "High expression of both USP4 and Twist1 was significantly associated with gene signatures of Notch and TNF signaling, suggesting that Twist1 may play a role in USP4-mediated lung cancer stemness." (PMID 32549341, 2020). "Thus, targeting the USP4–Twist1 axis may represent a novel therapeutic approach for lung cancer treatment." (PMID 32549341, 2020). "Notably, expression of USP4 was also significantly correlated with expression of Oct4 (R = 0.295; p < 0.001; n = 203) and Sox2 (R = 0.448; p < 0.001; n = 203), suggesting that USP4 is a potential positive regulator of lung cancer stemness." (PMID 32549341, 2020). "Thus, we investigated whether Snail1 also contributes to the reduction of USP4 expression in lung cancer cells." (PMID 31936290, 2020). "For example, USP4 and USP15 promoted the growth of lung cancer cells via measuring selective splicing of SRSF1." (PMID 38581057, 2024). "B-AP15 contributes to the selective inhibition of USP4 and UCHL5, and restrains the cell proliferation of various cancers, including lung cancer, CRC, BC, myeloma, prostate cancer, and liver cancer." (PMID 37251574, 2023). "The MIR99AHG/miR-136-5p/USP4/ACE2 signaling axis controls lung fibrosis and epithelial-to-mesenchymal transition, which prevents the progression of lung cancer to lung adenocarcinoma." (PMID 37275887, 2023). "We found that SRSF1 is upregulated in several lung cancer cells compared to the normal lung epithelial cells, similar to the USP15 and USP4 expression patterns." (PMID 35027535, 2022). "First, we examined the endogenous expression level in different lung cancer cells and found that both USP15 and USP4 overexpresses in the NSCLC cell lines; A549, H157, and H1299 compared to the normal lung epithelial L132 cell." (PMID 35027535, 2022). "We observed an increased endogenous expression of SRSF1 in lung cancer cells as well, and its overexpression significantly enhanced cancer cell phenotype and rescued the depletion effect of USP15 and USP4." (PMID 35027535, 2022). "Thus, targeting USP4 may represent a novel therapeutic approach for lung cancer treatment." (PMID 32549341, 2020).
lung carcinoma (continued). "However, Hwang and his colleague found that upregulated expression of USP4 can facilitate brain metastasis of lung cancer by stabilizing β-catenin expression and knockdown of USP4 showed an increased OS and brain metastasis-free survival which implied an opposite role of USP4 in lung cancer." (PMID 32669974, 2020). "However, whether USP4 directly regulates lung cancer stemness remains unclear." (PMID 32549341, 2020). "Mechanistically, USP4 can directly bind to the TRAF domain to inhibit TRAF2/TRAF6 activity through deubiquitination in an activity-dependent manner and negatively regulate IL-1β and TNF-α-induced NF-κB activation, thereby inhibiting lung cancer metastasis." (PMID 36969062, 2023). "This negative correlation suggests that USP4 expression is beneficial to lung cancer patient survival." (PMID 31936290, 2020). "Among DUBs analyzed, USP4 had the lowest negative Cox coefficient, suggesting a beneficial role of higher USP4 expression on lung cancer outcome." (PMID 31936290, 2020). "Thus, the mechanism for downregulation of USP4 and the functions of this DUB in control of inflammation, stemness, and lung cancer growth were further investigated experimentally both in culture and in mouse models of tumorigenesis and tumor growth." (PMID 31936290, 2020). "In this study, OncoLnc screening for DUBs potentially involved in lung cancer development revealed that USP4 has the strongest negative Cox coefficient, suggesting a protective effect of expression against lung cancer." (PMID 31936290, 2020).